APP (amyloid beta precursor protein)
Diseases named in the same sentence as APP in open-access papers (continued):
Sharing a sentence is not in itself a finding about the gene and the disease.
tauopathy (111 papers, 2006 to 2026). Neurodegenerative disorders involving deposition of abnormal tau protein isoforms (tau proteins) in neurons and glial cells in the brain. "Here, we characterize the APP695E590D mutation by evaluating multiple APP metabolites and determining its effects on tauopathy in cellular and animal models." (PMID 41816611, 2026). "Overall, most of these studies have been performed in amyloidogenic or tauopathy models that overproduce human amyloid precursor protein (APP) with mutations associated with familial AD or overexpressing mutated forms of tau." (PMID 40364523, 2025). "In rat primary cortical neurons, iron treatment resulted in the cellular retention of APP, thereby generating APP products susceptible to amyloidogenic processing in tauopathies." (PMID 30174587, 2018). "The elevated hyperphosphorylated tau is likely to promote neuronal cell death via tauopathy with tau-associated NFTs along with production of APP-derived toxic C-terminal C99 fragment, ultimately leading to neurodegeneration in HIV-1 Tg rats." (PMID 28107387, 2017). "We observed advanced signs of AD, including accelerated cerebral amyloid angiopathy (CAA), increased tauopathy, and increased neuronal loss in APP-Tg mice." (PMID 26728181, 2016). "In conclusion, our findings give support for an impairment of the autophagy-lysosomal system in patients with primary tauopathies as well as in familial AD caused by the Swedish APP mutation." (PMID 26936765, 2016). "Tauopathy is patho-diagnostically linked to all AD-cases, including early-onset cases due to mutations in APP or presenilins that are by definition caused by amyloid overproduction." (PMID 19794916, 2009). "Studies on antidiabetic treatments often use mouse models that replicate tauopathies by overexpressing human tau mutations (P301L and P301S), linked To neurodegeneration, as well as 3xTg-AD and tau-injected APP/PS1 mice that mimic both amyloid and tau pathologies." (PMID 41146261, 2025). "Moreover, deletion of C3 in mouse models of neuropathy (PS2APP and APP/PS) and tauopathy (TauP301S) rescued synapse loss and ameliorated neurone loss and brain atrophy, improving neurophysiological and behavioural measurements." (PMID 39426921, 2025). "Interestingly, this evidence supports more recent studies which suggest a prominent, causal role of APP accumulation in triggering synaptotoxicity and tauopathy." (PMID 32954296, 2020). "In view of the central role of the host-encoded proteins such as PrP in TSEs, amyloid precursor protein (APP) in AD and microtubule associated protein (tau) in AD, PD and tauopathies, these neurodegenerative diseases are grouped together as protein misfolding diseases." (PMID 26771599, 2016). "In addition to mis-splicing, defects in APP metabolism have been strongly associated with the development of some tauopathies, particularly AD [recently reviewed in Huang and Mucke (2012)]." (PMID 24409116, 2014). "Indeed, other tauopathies have been associated with mutations in different genes: APP, PS1, and PS2 (three genes involved in the amyloid cascade in AD); MAPT (Tau gene) (other mutations than those involved in splicing default), or the MAPT haplotype." (PMID 24409116, 2014). "Moreover, the reductions in Aβ accumulation that occur from the inhibition of APP processing lead to a dose- and time-dependent amelioration of tauopathy in the fAD organoids, suggesting a causal relationship between these relevant pathologies in the neural organoid model." (PMID 27622770, 2016). "The EFAD mouse line combining mutations in APP and PSEN1 with human APOE isoforms provides a platform to study the effects of APOE on Aβ deposition, tauopathy, neuroinflammation, and synaptic function." (PMID 40420360, 2025). "Single-cell RNA-seq elucidated cell-type-specific gene expression, and Connectivity Map (CMap) screening nominated candidate therapeutics validated in a tauopathy mouse model (AAV-hTau-injected APP/PS1 mice)." (PMID 41409615, 2025).
tauopathy (continued). "Changes in the ratio of protein isoforms produced by the genes APP and MAPT have strong associations with AD and other tauopathies." (PMID 39658200, 2024). "Here, authors use multi-omics to reveal the fly APP’s role in regulating proteostasis and validate using vertebrate and In-vivo tauopathy models." (PMID 37923712, 2023). "This increase is similarly observed in several transgenic mouse models of familial AD that overexpress mutant forms of APP including Tg2576, APP/PS1 and J20 mice as well as in tauopathy models carrying mutations in MAPT." (PMID 36449279, 2023). "C1q is upregulated in amyloidosis and tauopathy mouse models and our team observed that a deficiency of TYROBP induces a dramatic reduction of C1q in both APP/PSEN1 and MAPTP301S mice." (PMID 36002854, 2022). "Aβ is generated by proteolytic processing of amyloid beta precursor protein (APP), and accumulation of Aβ impairs memory, reduces the formation of dendritic spines, and increases neuroinflammation and tauopathy." (PMID 33709472, 2021). "In this study, we investigated the efficacy of curcumin analog C1 in three AD animal models, which represent the APP pathology (5xFAD mice), tauopathy (P301S Tau mice) and the APP/MAPT combined pathology (3xTg‐AD mice)." (PMID 31858697, 2020). "In this study, we systematically investigated the efficacy of curcumin analog C1 in three AD animal models that represent beta‐amyloid precursor protein (APP) pathology (5xFAD mice), tauopathy (P301S mice) and the APP/Tau combined pathology (3xTg‐AD mice)." (PMID 31858697, 2020). "The present study aimed to identify early behavioral and cognitive deficits in two transgenic mouse models of tauopathy and AD, respectively, more specifically Tau.P301L and APP.V717I × Tau.P301L mice." (PMID 31866856, 2019). "Previous studies have demonstrated that both exogenous Aβ infused through a needle and intrinsic Aβ derived from transgenic APP can exacerbate tauopathy in mouse models of FTLD." (PMID 27070146, 2016). "If the observations made in the neuronal culture system described here are replicated in vivo, then modulators of APP processing might hold promise for pure tauopathies, as well as AD." (PMID 37269953, 2023). "While this contradicts results in tauopathy and 5XFAD mice, it does align with other reports from the APP/PS1 model, indicating that strain may influence the infiltration of neutrophils in AD models." (PMID 35331340, 2022). "Indeed, AD is classified as a secondary tauopathy, as the mutations characterizing AD mainly affect the presenilin genes (PSEN1 and PSEN2) and the amyloid precursor protein gene (APP), resulting in an altered amyloid metabolism." (PMID 36499544, 2022). "In our study, when comparing the results from the P301S Tau mice and 5xFAD mice, C1 has stronger effects on attenuating tauopathy that APP turnover, indicating TFEB activation induced by C1 may primarily act on tauopathy." (PMID 31858697, 2020). "Enzymatic glycosylation may contribute to tauopathies by modifying proteins other than tau, such as APP and the β-site APP-cleaving enzyme 1 (BACE1)." (PMID 33488497, 2020). "It is commonly accepted that amyloidogenesis is associated with the production of Aβ peptides from its precursor protein APP by the consecutive actions of β- and γ-secretases, while tauopathy shows hyper-phosphorylation of tau protein in the brain of AD patients." (PMID 33329577, 2020). "Using a novel transgenic mouse line to model the impact of human APP (hAPP)/Aβ accumulation on tauopathy in the entorhinal cortex–hippocampal (EC-HIPP) network, we demonstrate that hAPP overexpression aggravates EC-Tau aggregation and accelerates pathological tau spread into the hippocampus." (PMID 32822389, 2020). "Therefore, the pathophysiology that differentiates AD from primary tauopathies is preferentially modeled by APPswe/PS1dE9 mice, which reproduce the temporal relationship between aberrant APP processing and tau aggregation in familial AD." (PMID 31673052, 2019).
tauopathy (continued). "Recent developments using vaccine-based approaches to both tauopathies and APP-related disorders may provide vehicles for such new treatments aimed at suppressing toxic proteins." (PMID 31849608, 2019). "First, the presence of mutations in the genes encoding presenilin 1 (PS1), amyloid precursor protein (APP), and tau (MAPT) have been identified as causing familial AD (PS1M146V, APPSWE) or tauopathies including frontotemporal dementia and parkinsonism linked to chromosome 17 (MAPTP301L)." (PMID 28774322, 2017). "To test whether tauopathy is induced in APP-Tg mice 1 year after being on HFD, we stained the brains of mice fed with either HFD or SD with an antibody that binds to pTau." (PMID 26728181, 2016). "Differences in clinical presentation of AD-like and FTLD syndromes are therefore likely to be inherent to the respective underlying tauopathy, and are not dependent on presence or absence of concomitant APP pathology." (PMID 25523019, 2015). "Our results regarding AP2B1 and APP suggest that the early stages of the lysosomal pathway are specifically altered in the FTLD-linked disorders (and potentially particularly the primary tauopathies) when compared to those disorders with underlying AD pathology." (PMID 37917233, 2024). "Thus, tauopathy in the brain may be aggravated by the increased production or accumulation of APP fragments in vivo through direct interaction." (PMID 32822389, 2020). "However, in other tauopathies such as AD and PD, neurodegeneration may be mediated through interactions with key disease-relevant proteins such as ApoE4, APP or α-synuclein." (PMID 30174587, 2018). "Thus, if CAA and tauopathy represents advanced AD, one may argue that AD accelerated more dramatically in WT mice than APP-Tg mice, and it may be regulated differently in genetically predisposed (APP-Tg) vs. non-predisposed individuals (WT)." (PMID 26728181, 2016). "Our group validated this observation in an APP/PSEN1 model of amyloidopathy and in a model of tauopathy, where complete deletion of Tyrobp is phenotypically beneficial." (PMID 38459557, 2024). "In contrast, inhibition of C3aR reduced glial activity and rescued neuronal defects in a tauopathy model (PS19 mice), and C3aR antagonist-treated APP-transgenic mice had a reduced plaque burden compared to control AD mice." (PMID 38840206, 2024). "Consistent with a possible protective effect of deferasirox in tauopathy are the trends toward relatively better memory, in both CFC cue and context tests, in both Tau/Tau and Tau/APP mice." (PMID 35327557, 2022). "Learning behavior and synaptic electrophysiological function were preserved at normal physiological levels even in the face of robust cerebral amyloidosis (in APP/PSEN1;Tyrobp−/− mice) or tauopathy (in MAPTP301S;Tyrobp−/− mice)." (PMID 36002854, 2022). "Hippocampal expression of IL-1β was shown to robustly reduce plaques in the APP/PS1 model and 3xTg-AD model but worsened tauopathy in the 3xTg-AD model." (PMID 35897046, 2022). "These biomarkers mainly mirror the endpoint of amyloid precursor protein (APP) metabolism and tauopathy." (PMID 34412639, 2021). "The effects of C1 on three AD animal models, which represent beta-amyloid precursor protein (APP) pathology (5xFAD mice), tauopathy (P301S mice) and the APP/Tau combined pathology (3xTg-AD mice), were investigated." (PMID 33562649, 2021). "APP and BACE1 have been found to be O-glycosylated and N-glycosylated in tauopathy patients' brains." (PMID 33488497, 2020). "For instance, differential exon inclusion in the amyloid precursor protein (APP) influences Aß peptide production, while the MAPT gene’s 3 R/4 R tau isoform balance is central to tauopathy pathogenesis; an instability in these isoforms is a characteristics of AD pathology." (PMID 40600167, 2025).
tauopathy (continued). "Numerous studies have suggested that procyanidins may improve AD-related brainneuropathology by preventing the production of toxic peptides such as amyloidprecursor protein (APP) processing, amyloid-protein build-up, and tauopathy." (PMID 39504064, 2024). "Similarly, it has been shown that TREM2 downregulation affects the phenotype of GFAP-positive astrocytes in the APP/PS1 amyloid mouse model and the PS19 model of tauopathy." (PMID 37371067, 2023). "Specifically, APP-transgenic mice are models of the presymptomatic phase of AD with cerebral β-amyloidosis and early changes of tauopathy, but mice do not develop human-like neurofibrillary lesions and the symptomatic phase of AD." (PMID 36443293, 2022). "As the 5XFAD mouse model was originally designed for the investigation of APP- and Aβ-related pathology, this model is not expected to develop significant tauopathy in the brain." (PMID 33452414, 2021). "C1, an mTOR-independent activator of TFEB, efficiently reduces APP, APP C-terminal fragments (CTF-β/α), Aβ and Tau aggregates in three AD animal models, such as beta-amyloid precursor protein pathology (5xFAD mice), tauopathy (P301S mice) and the APP/Tau combined pathology (3xTg-AD mice)." (PMID 33292395, 2020). "Although these double-transgenic AD mouse models, with only APP and PS1 mutation, are not exact replicable models of tauopathy, they have the potential to exhibit hyperphosphorylated tau as punctuate deposits and neurofibrillary changes." (PMID 32733573, 2020). "The inhibition of the APP IRES and tau IRES by memantine might indicate the diminished Aβ production and tauopathies as well as an antagonist of NMDA receptors in AD." (PMID 25903151, 2015). "AD is characterized by two proteinopathies: amyloidopathy, a product of the abnormal cleavage of the amyloid precursor protein (APP), which leads to the accumulation of Aβ peptide in senile or amyloid plaques; and tauopathy, which is due to Tau hyperphosphorylation and aggregation." (PMID 25225483, 2014). "Motor disabilities are not clinical features only in APP-based AD transgenic models but also in PS19 mice, a tauopathy AD model with observed motor decline and walking impairment at nine months of age." (PMID 36555237, 2022).
Parkinson disease (97 papers, 2008 to 2026). A progressive degenerative disorder of the central nervous system characterized by loss of dopamine producing neurons in the substantia nigra and the presence of Lewy bodies in the substantia nigra and locus coeruleus. "LINGO1 promotes APP degradation, contributing to Aβ deposition Aβ and its up-regulation is implicated in AD and Parkinson’s disease." (PMID 39868232, 2025). "Corynoxine can regulate several kinases, including RPS6KB1, MAP2K2, and PLK1, contributing to the clearance of AD-associated β-amyloid precursor protein (APP) and Parkinson disease-associated α-synuclein." (PMID 33807157, 2021). "We investigated the effect of APP over-expression in the loss of neurons upon exposure to the mitochondrial neurotoxin and Parkinson’s disease mimetic rotenone." (PMID 30612335, 2019). "Because tau deficiency inhibits APP trafficking to the membrane, it cannot interact with ferroportin and inhibits iron efflux from neurons, which results in intracellular iron accumulation and dopaminergic neuronal death, Parkinsonism and dementia." (PMID 40438504, 2025). "In addition, in amyotrophic lateral sclerosis, endosomes accumulate APP in motor neurons reflecting impaired vesicle trafficking, while in Parkinson’s disease, α-synuclein multimers cause synaptic vesicles to cluster and traffick to be attenuated." (PMID 28153028, 2017). "Reelin has been implicated in APP/Aβ protein processing and regulation of TAU phosphorylation, as observed in AD and Parkinson’s disease." (PMID 40867631, 2025). "IRE-containing mRNAs have been found in a variety of other proteins recently, including α-synuclein in Parkinson disease, α-hemoglobin stabilizing protein, and Alzheimer’s amyloid precursor protein (APP)." (PMID 40438504, 2025). "Genetic mutations and protein abnormalities linked to diseases like Alzheimer’s (APP, PSEN1, PSEN2), Parkinson’s (PINK1, LRRK2), and Huntington’s (HTT) can be detected in fibroblasts, reflecting similar changes in brain pathology." (PMID 39766775, 2024). "The molecular mechanism revealed that rTMS results in the reduction of APP through the inhibition of the MKK7-ERK1/2-c-FOS-APP axis in a 6-OHDA-induced mouse model of Parkinson’s disease." (PMID 36614120, 2022). "Parallel with iron accumulation, it has been observed a reduction of Tau and amyloid precursor protein (APP) levels within the brain of Parkinson’s patients." (PMID 28651647, 2017). "APP (amyloid beta precursor protein) and SNCA (alpha-synuclein), which are implicated, respectively, in Alzheimer’s and Parkinson’s diseases, are a case in point." (PMID 29250101, 2017). "Several mutations that are responsible for early onset forms of Alzheimer or Parkinson disease have been isolated in the coding sequences of corresponding amyloid proteins (amyloid precursor protein APP, and alpha-synuclein, respectively)." (PMID 19262694, 2009). "Here, we use the plant-derived pesticide rotenone, a potent complex I-specific inhibitor, and Parkinson’s disease mimetic, to discover neuroprotective effects of APP and sAPPα in vitro and in vivo and provide mechanistic insights into the role of APP in counteracting mitochondrial neurotoxic stress." (PMID 30612335, 2019). "Interestingly, APP phosphorylation at T668 seems to play a role in the pathogenesis of Parkinson’s disease (PD)." (PMID 31892243, 2019). "Few studies have investigated APP levels in Parkinson’s disease brain." (PMID 30612335, 2019). "Here we identified that an anti-Parkinson’s disease drug, Istradefylline, could enhance Aβ generation in various cell lines and primary neuronal cells of APP/PS1 mouse." (PMID 27835671, 2016). "Both paroxetine and NAC subsequently displayed in vivo anti-amyloid efficacy in APP transgenic mice, an approach we extended to the use of agents of potential benefit to Parkinson's disease patients for whom proven FDA drugs limited the translation of SNCA mRNA by targeting SNCA 5′UTR sequences." (PMID 23935819, 2013).